IDH1 (isocitrate dehydrogenase (NADP(+)) 1)
Diseases named in the same sentence as IDH1 in open-access papers (continued):
Sharing a sentence is not in itself a finding about the gene and the disease.
prostate carcinoma (28 papers, 2016 to 2026). A carcinoma that arises from epithelial cells of the prostate gland. "Our simulations revealed prolonged AR inhibition causes significant dysregulation of TGF-β, IDH1, and cell cycle pathways specifically in AA prostate cancer." (PMID 38566104, 2024). "We used this database (10x Genomics) to analyze the potential associations between IDH1 and the tumor microenvironment in prostate cancer." (PMID 35132321, 2022). "Overall, the analysis of this data set revealed that IDH1 upregulation is associated with prostate cancer and plays an important role in tumor progression." (PMID 35132321, 2022). "In a few cases, other types of cancers carried IDH1/2 mutations, such as paraganglioma, colon cancer, prostate cancer, and lung cancer." (PMID 31847543, 2020). "The presence of IDH1 mutations appears to represent a rare and unique subset of early onset prostate cancers, with relatively few SCNAs and high levels of genomic hypermethylation." (PMID 29581876, 2018). "IDH1, which encodes a metabolic enzyme, is recurrently mutated in prostatic cancers, resulting in a methylator phenotype." (PMID 29581876, 2018). "IDH1/IDH2 genes are mutated in 1–3% of all prostate cancer cases." (PMID 31366128, 2019). "This study identifies a compensatory shift in α-ketoglutarate (α-KG) metabolism in prostate cancer, where the tumor relies on IDH1 to incorporate citrate into the TCA cycle." (PMID 42225654, 2026). "Our observations provide a rationale to measure gene expression changes in TGF-β, IDH1, and cell cycle pathways, in prostate cancer of AA and EA men treated with AR inhibitors." (PMID 38566104, 2024). "We confirmed that IDH1 mRNA levels were significantly higher in prostate cancer cell lines, in accordance with the other data sets." (PMID 35132321, 2022). "We also found a significant enrichment of IDH1 dependence in prostate cancer cell lines in the CRISPR-Cas9 data set." (PMID 35132321, 2022). "Specifically, among prostate cancer cell lines, six out of eight (75%) prostate cancer cell lines were dependent on IDH1." (PMID 35132321, 2022). "According to these observations it concluded that AR reprograms prostate cancer cell metabolism, favoring extramitochondrial IDH1-mediated IDH activity." (PMID 31366128, 2019). "As expected, the IDH1-mutant subset harbored the greatest number of epigenetically silenced genes among all prostatic cancers." (PMID 29581876, 2018). "Thus, we searched for germinal variants in ASXL1, CHD1, IDH1, SETD2 and TET2 epigenetic genes in Polish prostate cancer patients and controls and analyzed the impact of them on disease clinical course, including overall survival time." (PMID 39529133, 2024). "Oxalomalic acid mimics the effects of IDH1 inhibition on prostate cancer cell lines and could ameliorate the pathology of prostate cancer cells." (PMID 35132321, 2022). "A study of a cohort of 333 primary prostate carcinomas showed that 74% of these tumors fell into one of seven subtypes of a molecular taxonomy defined by specific gene fusions (ERG,ETV1/4 and FLI1) or mutations (SPOP,FOXA1 and IDH1)." (PMID 33058520, 2020). "Based on genomic profiles, prostate cancer can be divided into seven molecular subtypes which bear distinct oncogenic drivers including fusions with ETS family members (ERG, ETV1, ETV4, and FLI1) and mutations in SPOP, FOXA1, and IDH1." (PMID 33273988, 2020). "An earlier study of a cohort of 333 primary prostate carcinomas showed that 74% of these tumors fell into one of seven subtypes of a molecular taxonomy defined by specific gene fusions (ERG, ETV1/4 and FLI1) or mutations (SPOP, FOXA1 and IDH1)." (PMID 33058520, 2020). "Interestingly, prostate cancers display the highest IDH1 expression levels across the human cancer spectrum and IDH1 expression increases during porstate cancer progression." (PMID 31366128, 2019).
prostate carcinoma (continued). "Overall, these findings uncover a metabolic adaptation in response to IDH1 inhibition and highlight the pivotal role of c-Fos in mediating this compensatory pathway, offering new insights into potential metabolic targets for prostate cancer treatment and ferroptosis-based therapies." (PMID 42225654, 2026). "In an analysis of 333 individual prostate cancer exomes, TCGA identified seven subtypes defined either by gene fusions involving the ETS family (59% of cases), specifically ERG, ETV1, ETV4, or FLI1, or recurrent mutations (15% of cases) in SPOP, FOXA1, or IDH1." (PMID 28423598, 2017). "Targeting α-KG-metabolizing enzymes, such as IDH1 or GLUD1, presents promising therapeutic strategies for prostate cancer subtypes by inhibiting tumor proliferation and inducing oxidative stress, thus sensitizing tumors to ferroptosis." (PMID 42225654, 2026). "In prostate cancer, high expression of SKP2 leads to IDH1 degradation, enhances glycolysis and promotes tumor proliferation." (PMID 40534867, 2025). "Also in prostate cancers, tumor progression is led by an integrated signaling between androgen receptors (AR) and the extra-mitochondrial IDH1 activity, suggesting that targeted IDH1 therapies may be a possible therapeutic approach." (PMID 39123479, 2024). "Utilization of our patient-specific prostate cancer Boolean networks revealed the potential role of prolonged AR therapy in inducing gene expression changes in TGF-β, IDH1, and cell cycle pathways specifically in prostate cancer of AA men." (PMID 38566104, 2024). "In prostate cancer, high expression of SKP2 leads to IDH1 degradation." (PMID 40534867, 2025).
myeloid malignancies (26 papers, 2012 to 2025). "The IDH1/2‐TET2‐WT1 pathway in myeloid malignancies explains the mutual exclusivity of IDH1/2, WT1, and TET2 mutations." (PMID 40599235, 2025). "Loss of TET2 function caused by the TET2 gene and IDH1/2 mutations is common in myeloid malignancies and lymphomas." (PMID 35223782, 2022). "Thirty-one patients with advanced IDH1-mutated myeloid malignancies were treated within four separate cohorts, two of which received VEN 400 mg or 800 mg once daily (D1–14 every 28 days) in combination with IVO 500 mg once daily (administered continuously beginning on C1D15)." (PMID 37509251, 2023). "Furthermore, we found that the IDH1/2 point mutations, common in both glial and myeloid malignancies, also disrupt PML-NBs demonstrating that a range of disparate mutations converge on PML." (PMID 38066546, 2023). "Interestingly, glial and myeloid malignancies are both also frequently mutated in IDH1 and IDH2." (PMID 38066546, 2023). "In the absence of these three major driver mutations, screening for other mutations associated with myeloid neoplasms, such as ASXL1, EZH2, TET2, IDH1, IDH2, SRSF2, and SF3B1, can help establish the clonal nature of the disease." (PMID 41514563, 2025). "Some investigations reported the co-occurrence of ASXL1 mutations with EZH2, IDH1/2, RUNX1, and TET2 in myeloid malignancies." (PMID 38807730, 2024). "Ivosidenib, a selective IDH1 inhibitor, is also under investigation in a phase 1 study (NCT03564821) as maintenance therapy after allo-HCT for IDH1 mutated myeloid neoplasms." (PMID 36016625, 2022). "(iii) IDH1 and IDH2 mutations are also rarely present in preleukemic myeloid malignancies: 0.8–4% in chronic phase MPN, 4–14% in MDS, but its frequency increases up to 20–25% in blast phase transformation." (PMID 34153064, 2021). "The hypomethylating agents 5-azacytidine and decitabine show efficacy in myeloid neoplasms such as AML, and the response rate to these drugs appears to correlate with TET2, IDH1/2, and/or DNMT3A mutations." (PMID 33292562, 2020). "The orally available IDH1 inhibitor ivosidenib (IVO) demonstrated efficacy as a single agent in both ND and R/R-AML, and was evaluated in combination with VEN with or without AZA in a PIb/II study of IDH1-mutated myeloid malignancies." (PMID 37509251, 2023). "Several mutant IDH1 inhibitors have entered clinical trials for hematologic malignancies, while only ivosidenib has been proposed as wild-type inhibitor in myeloid neoplasms (NCT03564821)." (PMID 34880756, 2021). "In support of this possibility, mutations of IDH1 and IDH2 also occur in myeloid malignancies where neomorphic activity of the enzyme results in aberrant generation of 2-hydroxyglutarate, which inhibits the 2-oxoglutarate dependent conversion of 5mC to 5hmC by TET2." (PMID 25276435, 2014). "Around 60% of CD34+ cells from patient 2 [P2(h)] exhibited a heterozygous JAK2V617F mutation (JAK2V617F/WT) whereas no mutation was identified in these cells in ASXL1 and the other genes involved in myeloid malignancies, including TET2, EZH2, DNMT3A, IDH1 and SRSF2." (PMID 24066127, 2013).
low grade glioma (24 papers, 2018 to 2025). A grade I or grade II glioma arising from the central nervous system. "A particular SNP in intron 2 of LRIG1, rs11706832, has been shown to increase the susceptibility for IDH1 mutated low-grade gliomas (LGG)." (PMID 37185361, 2023). "Approximately 80% of low-grade glioma (LGGs) harbor mutant isocitrate dehydrogenase 1/2 (IDH1/2) driver mutations leading to accumulation of the oncometabolite 2-hydroxyglutarate (2-HG)." (PMID 33668509, 2021). "Mutations in the enzyme isocitrate dehydrogenase 1/2 (IDH1/2) are the most common somatic mutations in low-grade glioma (LGG)." (PMID 33195240, 2020). "Expression of IDH1-wt caused hypomethylation, while expression of IDH1-R132H hypermethylated CpG island in proneural, similar to what was observed in low-grade glioma (LGG) containing the IDH1-R132H mutation." (PMID 33221817, 2020). "• Mutations in IDH1 and IDH2 havebeen evidenced inover 80% of low-grade gliomas (LGGs) and secondary GBM." (PMID 35786935, 2022). "The most important IDH mutation in GBM is IDH1-R132H, which was introduced in the 2016 WHO Classification for Tumors of the Central Nervous System as the molecular marker of low-grade glioma (LGG) and secondary GBM." (PMID 36361838, 2022). "Low-grade gliomas (LGG) have a unique molecular footprint, characterized by IDH1/2 mutation status and codeletion in chromosome 1p and19q regions of the genome." (PMID 33272320, 2020). "Somatic mutations of the isocitrate dehydrogenase 1 and 2 genes (IDH1 and IDH2) are frequent and early events in the pathogenesis of low-grade gliomas as well as in a small subset of GBMs." (PMID 30567605, 2018). "Mutations in the IDH1/2 have been identified in gliomas, and IDH-mutant low-grade gliomas (LGGs) may develop malignant transformation after further genetic alterations, such as Myc, PTEN, KRAS, PIK3CA, and MET, are acquired." (PMID 37063420, 2023). "Mutations in isocitrate dehydrogenase 1 and 2 (IDH1/2), mainly Arg132 for IDH1 and Arg140 and Arg172 for IDH2, occur in over 80% of low-grade glioma (LGG)." (PMID 33195240, 2020). "Unlike low-grade glioma (LGG), GBM cancer cell lines do not have IDH1 mutants available for experimental applications." (PMID 31450822, 2019).
Ollier disease (23 papers, 2013 to 2026). A rare primary bone dysplasia disorder characterized by the development of multiple mainly unilateral or asymmetrically distributed enchondromas throughout the metaphyses of the long bones. "Except in Gorlin syndrome, for which PTCH1 variants have been reported, only few gene variants have been described in fibromas: a SMARCA4 variant associated with PTCH1 variant in one case and an IDH1 variant associated with Ollier disease in one case." (PMID 38136408, 2023). "Our results suggest that while IDH1 is a known pathogenic gene in enchondromatosis, ERC2 is a novel gene identified in Maffucci’s syndrome." (PMID 34790172, 2021). "The IDH1 R132C mutation was detected in most of the patients with Ollier disease (51/69 patients), and the mean frequency of this mutation was 63.3% in total sequence readouts, but the ECR2 L309I mutation was absent in all of the patients with Ollier disease." (PMID 34790172, 2021). "Patients with Ollier disease and Maffucci syndrome, due to somatic gain-of-function mutations in IDH1 or IDH2, develop enchondromas." (PMID 24875294, 2014). "A 38-year-old man was affected, since he was an infant, by Ollier disease, mainly localized in both hands, treated through microsurgical resection of multiple enchondromas of the fingers and whose molecular examination revealed the IDH1 R132H mutation." (PMID 39335096, 2024). "The incidence of ovarian juvenile granulosa cell tumors with Ollier’s disease in children may be caused by generalized mesodermal dysplasia; IDH1 gene mutation may play a facilitated role in this process." (PMID 37324278, 2023). "The etiology of Ollier disease is unknown, but it is linked with somatic heterozygous mutations in IDH1 or IDH2 genes." (PMID 34393643, 2021). "Zhang and Alman reviewed genetic findings in enchondromatosis and found somatic mutations in IDH1/2 to be the most common abnormality and suggest that pharmacologic therapies could target this gene or downstream pathways affected by the mutation." (PMID 34198529, 2021). "The estimated prevalence of Ollier disease is 1 in 100,000 and while it is linked with somatic heterozygous mutations in IDH1 or IDH2 genes, exact etiology is unknown." (PMID 34393643, 2021). "Indeed, IDH1 or IDH2 heterozygous mutations have been described in Ollier disease (81% carried IDH1/2 mutations in their tumors) and Maffucci syndrome (77%), that are usually non-hereditary skeletal disorders." (PMID 31010244, 2019). "Ollier disease is brought about by an early postzygotic mutation in IDH1 or IDH214." (PMID 28834325, 2017). "Based on the identification of histone mutations in neurogenerative developmental disorders, it is tempting to speculate that selected orphan bone syndromes could also be caused by histone mutations or other epigenetic alterations, such as Ollier disease/Maffucci Syndrome caused by IDH1/2 mutations." (PMID 37828086, 2025). "Somatic IDH1 and IDH2 variants have been found in cases of juvenile granulosa cell tumors associated with Ollier disease or Maffucci syndrome." (PMID 38136408, 2023). "It is clear that somatic mosaic isocitrate dehydrogenase type 1 (IDH1) and isocitrate dehydrogenase type 2 (IDH2) mutations are associated with Maffucci’s syndrome and Ollier disease." (PMID 34790172, 2021). "Patient CS04, who also has Ollier disease, had a GI CS and IDH1 mutant molecules detectable in plasma postoperatively on three different time points." (PMID 28834325, 2017). "It has been clear that somatic mosaic isocitrate dehydrogenase type 1 (IDH1) or isocitrate dehydrogenase type 2 (IDH2) mutations are associated with Maffucci’s syndrome and Ollier disease, but the mechanisms underlying hemangiomas of the Maffucci’s syndrome is still obscure." (PMID 34790172, 2021).
Ollier disease (continued). "It will be of interest to determine whether mutations in IDH1 or IDH2, which cause Ollier disease and Maffucci syndrome, affect chondrocyte organization and terminal differentiation in a similar manner to SHP2 depletion." (PMID 24875294, 2014). "JGCTs may occur in enchondromatosis-associated Ollier disease and Maffucci syndrome, both representing likely nonhereditary conditions, in which somatic IDH1 and IDH2 mutations have been reported." (PMID 37796616, 2023). "A c.394C>T (p.Arg132Cys) mutation of the IDH1 gene was detected in both the ovarian JGCTs and enchondromatosis but not detected in the peripheral blood, skin tissue, muscle tissue, and oral mucosa samples of the patient, nor in the peripheral blood of the parents of the patient." (PMID 37324278, 2023). "Excitingly, the IDH1 R132C mutation was detected in most of the patients with Ollier disease (51/69 patients), and the mean frequency of this mutation was 63.3% in total sequence readouts, but the ECR2 L309I mutation was absent in all of the patients with Ollier disease." (PMID 34790172, 2021).